RNU4-14P (RNA, U4 small nuclear 14, pseudogene)
Gene: Small nuclear RNA gene on chromosome 5 (140,397,323 to 140,397,444, reverse strand). Ensembl gene ENSG00000222790.
Homologues: Orthologues: chimpanzee U4 (97% identical), macaque U4 (72% identical), guinea pig U4 (59% identical). Paralogues in human: RNU4-41P (63% identical), RNU4-67P (63% identical), RNU4-73P (62% identical), RNU4-80P (62% identical), RNU4-84P (61% identical), RNU4-12P (61% identical), RNU4-44P (61% identical), RNU4-76P (61% identical), RNU4-78P (61% identical), RNU4-7P (61% identical), RNU4-16P (60% identical), RNU4-58P (60% identical), and 81 more.